NEFL (neurofilament light chain)
Diseases named in the same sentence as NEFL in open-access papers (continued):
Sharing a sentence is not in itself a finding about the gene and the disease.
neurological diseases (continued). "Serum neurofilament light chain (sNfL) is widely regarded as a potential biomarker for various neurological diseases." (PMID 39239395, 2024). "In routine clinical practice, serum neurofilament light chain (sNfL) has emerged as a promising biomarker for a multitude of nervous system diseases." (PMID 38308244, 2024). "The neurofilament light chain (NfL) has been studied extensively for many neurological disorders and has been shown to be a dynamic biomarker that changes with disease progression." (PMID 38734978, 2024). "The neurofilament light chain (NfL) is a biomarker that can detect axonal damage in different neurological diseases." (PMID 39337499, 2024). "Neurofilament light chain (NFL) is a biomarker that can indicate neurodegeneration in various neurological disorders." (PMID 38891863, 2024). "Neuronal damage assessed by Neurofilament light chain (NfL), a neurone-specific cytoskeletal protein, is reflected in clinical and imaging measurements of illness across different neurological diseases." (PMID 39595521, 2024). "Serum neurofilament light chain (sNfL) is a protein released into the bloodstream following nerve axon injury and has been validated as a reliable biomarker for various neurological diseases." (PMID 39381758, 2024). "In contrast, the neurofilament light chain (NfL) is a biomarker that can detect axonal damage in many neurological diseases." (PMID 39337499, 2024). "In the last decade, neurofilament light chain (NfL) has been intensively investigated as a biomarker in several neurological diseases." (PMID 37259091, 2023). "Neurofilament light chain (NfL) has been investigated successfully as a biomarker of neurodestruction in various neurological diseases." (PMID 36624182, 2023). "Analysis of serum neurofilament light chain (sNFL), which reflects axonal damage in a wide variety of neurological disorders, tends to show increased levels in patients with higher grade nAE with significant differences at last visit (p < 0.01)." (PMID 36794673, 2023). "In this aim, we made use of neurofilament light chain (NfL) levels in plasma and serum of patients, a relevant biomarker for axonal injury in neurological diseases, quantified by an ultrasensitive single-molecule array (Simoa) assay recently developed." (PMID 36993944, 2023). "Serum neurofilament light chain (sNfL) is becoming a widely accepted marker for neuronal axonal damage in numerous neurological diseases, such as amyotrophic lateral sclerosis or multiple sclerosis." (PMID 36479924, 2023). "Serum neurofilament light chain (sNfL) is a biomarker for neuroaxonal damage and has been found to be elevated in several neurological diseases with neuronal destruction." (PMID 36479924, 2023). "Neurofilament light chain (NfL) is becoming increasingly notable in neurological diseases including AD, and it has been suggested as a new peripherical biomarker of neurodegeneration." (PMID 35288777, 2022). "Neurofilament light chain (NfL) is a well-characterised marker for axonal damage in neurological diseases." (PMID 36009416, 2022). "Neurofilament light chain (NF-L) concentration is recognized to be modified in neurological diseases and traumatic brain injuries, but studies in the normal aging population are lacking." (PMID 35018623, 2022). "Neurofilament light chain (NfL), released during central nervous injury, has evolved as a powerful serum marker of disease severity in many neurological disorders, including infectious diseases." (PMID 35750882, 2022). "The neurofilament light chain (NfL) is a promising biomarker in the diagnosis, prognosis, and treatment response evaluation of neurological diseases." (PMID 35490364, 2022). "Recently, neurofilament light chain protein (NfL) has been explored as a potential blood biomarker for monitoring neurodegeneration in patients with a variety of neurologic diseases including CALD." (PMID 35269535, 2022).
neurological diseases (continued). "Among the biomarkers that can detect neurological diseases already in their preclinical phase, neurofilament light chain (NfL) has given the most promising results." (PMID 34108859, 2021). "Serum neurofilament light chain (sNfL) is a marker of neurodegeneration in several neurological diseases." (PMID 34867740, 2021). "Following neuroaxonal damage, increased concentrations of neurofilament light chain (NfL) and phosphorylated neurofilament heavy chain (pNfH) have been reported in both CSF and blood in various neurologic disorders." (PMID 33889072, 2021). "Of the family of neurofilament proteins, neurofilament light chain (NfL) has gained the most interest as a candidate marker of outcomes in neurological diseases." (PMID 33233404, 2020). "Analogous to the cardiologist’s troponin, neurofilament light chain is a structural axonal protein that can be detected in the blood at elevated levels in a variety of neurological disease states which can be followed longitudinally." (PMID 33233404, 2020). "Serum neurofilament light chain (sNfL) and its ability to expose axonal damage in neurologic disorders have solicited a considerable amount of attention in blood biomarker research." (PMID 33203974, 2020). "In treatment-refractory antibody-mediated neurological disorders, daratumumab treatment has been associated with reductions in CD38-expressing T cells, NK cells, and serum neurofilament light chain levels, suggesting immunomodulatory effects and attenuation of active axonal injury." (PMID 41221291, 2025). "Serum neurofilament light chain (sNfL) is a biomarker of neurologic diseases." (PMID 40264648, 2025). "Serum neurofilament light chain (sNfL) has been identified as a biomarker for neurologic diseases." (PMID 39049062, 2024). "The neurofilament light chain (NfL) is a cytoskeletal intermediate filament protein of central and peripheral neurons, whose detection in blood has been validated as a nervous system damage biomarker in a variety of neurological diseases." (PMID 39125829, 2024). "Similarly to GFAP, another plasma biomarker that is altered across several neurological disorders is neurofilament light chain (NfL)." (PMID 38623387, 2024). "However, neurofilaments are not specific to MN and it is notable that serum neurofilament light chain (NfL) is elevated in other neurological diseases." (PMID 39649175, 2024). "Neurofilament light chain (NfL) is a biomarker for axonal damage in several neurological disorders." (PMID 38518653, 2024). "Neurofilament light chain (NfL) reflects axonal damage in neurological disorders." (PMID 36689008, 2023). "Aiming to identify biomarker allowing to predict relapse, we measured both myelin oligodendrocyte glycoprotein antibodies and neurofilament light chain levels in blood samples of patients that are known to reflect axonal injuries in neurological diseases including demyelinating autoimmune disorders." (PMID 36993944, 2023). "Antibodies to NEFL aggravate neurological disease and may be involved in neurodegeneration progression." (PMID 36282532, 2022). "Phosphorylated‐neurofilament heavy chain (p‐NfH) and neurofilament light chain (NfL) are neuron‐specific components of the cytoskeleton and may represent reliable markers of neuronal injury in neurological disorders." (PMID 33609080, 2021). "Neurofilament light chain (NfL) is a 61 kDa subunit constituent of a heteropolymer in neurofilament (Nf), a CNS cell-type specific protein, and a dominant component of the axonal cytoskeleton that have been thoroughly studied as a surrogate axonal degeneration marker in neurological diseases." (PMID 38248261, 2024). "Neurofilament light chain (NFL) is a neuronal protein, exclusively located in the neuronal cytoplasm, whose levels increase in serum and cerebrospinal fluid (CSF) proportionally to the degree of neuronal axonal damage, and it is a valuable biomarker in several neurological disorders." (PMID 36982552, 2023).
neurological diseases (continued). "Neurofilament subunits, mainly neurofilament light chain (NFL) and phosphorylated neurofilament heavy chain (pNFH), are actively involved in the pathogenesis of axonal injury and degeneration both as causative agents and progression markers for neurological diseases." (PMID 27965574, 2016). "Blood and CSF assays for neurofilament light chain (NfL) and GFAP increase with CNS tissue injury and have been evaluated across CNS tumors and other neurological diseases." (PMID 41583439, 2025). "Blood-based biomarkers reflecting neuronal and astroglial injury, such as neurofilament light chain (NfL) and glial fibrillary acidic protein (GFAP), have been exploited in healthy subjects and a variety of neurological disorders including TBI." (PMID 40514556, 2025). "Neurofilament light chain (NFL) is only found in the axons and fibers of neurons and is usually increased in cases of brain damage or neurological diseases." (PMID 39347154, 2024). "Especially, serum neurofilament light chain (NfL) levels have not yet been systematically studied in nitrous oxide induced neurological disorders." (PMID 41250261, 2025). "Neurofilament light chain (NfL), a marker of axonal damage, is elevated in cerebrospinal fluid and blood across various neurological diseases, but is not specific to a particular disease." (PMID 39297986, 2024). "More recently, neurofilament light chain (NfL) has been identified as a nonspecific marker of neurodegeneration in multiple neurological disorders." (PMID 37340685, 2023). "In addition, we could identify protein neurofilament light chains (NFL), known as a robust biomarker for TBI and other neurological disorders." (PMID 35409261, 2022). "In this regard, Neurofilament Light Chain (NfL) has been recognized as a non-specific marker indicative of axonal damage in different neurological diseases, whereas it is not fully understood whether and how its concentration changes after rehabilitation treatment." (PMID 38327625, 2024). "In addition to pathology-specific CSF biomarkers, neurofilament light chain (NfL), a nonspecific marker of axonal degeneration, has attracted increasing attention as a sensitive biomarker of disease severity and progression in many neurological disorders." (PMID 36071460, 2022).
peripheral neuropathy (71 papers, 2017 to 2026). A disorder affecting the peripheral nervous system. "The aim of this study is to identify the factors associated with peripheral neuropathy and to explore neurofilament light chain (NfL) as a biomarker for peripheral neuropathy (PN) in effectively virologically suppressed adults living with HIV." (PMID 38275937, 2023). "The findings of this systematic review and meta-analysis support the use of neurofilament light chain as a blood-based measure associated with the presence of neuronal injury in patients with peripheral neuropathy." (PMID 36574244, 2022). "Recently, it has been shown that serum neurofilament light chain (NfL), a biomarker of axonal nerve damage, correlates with axonal loss from sural nerve biopsies, thus providing pathological evidence of the validity of NfL in quantifying axonal damage in peripheral neuropathies." (PMID 33498362, 2021). "Serum neurofilament light chain (sNfL) has emerged as a promising biomarker for various neurological conditions, including peripheral neuropathy (PN)." (PMID 41263294, 2026). "The clinical utility of serum neurofilament light chain (sNfL) in the evaluation and management of peripheral neuropathy (PN) remains poorly defined." (PMID 41263294, 2026). "In a community update to the HD community by the sponsor, an increase in serum neurofilament light chain (NfL) and neurological symptoms and nerve conduction studies consistent with peripheral neuropathy were reported in branaplam-treated individuals." (PMID 40343270, 2025). "Blood biomarkers, including neurofilament light chain (NfL), have garnered attention as potential indicators for chemotherapy-induced peripheral neuropathy (CIPN), a dose-limiting adverse effect of neurotoxic anticancer drugs." (PMID 38133405, 2023). "Neurofilament light chain was the most commonly reported marker (17 studies) and demonstrated significantly increased serum or plasma concentrations in patients with peripheral neuropathy compared with controls." (PMID 36574244, 2022). "Patients with peripheral neuropathy demonstrated significantly higher levels of neurofilament light chain compared with controls (standardized mean difference [SMD], 0.93 [95% CI, 0.82 to 1.05]; P < .001)." (PMID 36574244, 2022). "We aimed to evaluate the potential of serum neurofilament light chain (sNfL) and serum brain-derived neurotrophic factor (sBDNF) as reliable biomarkers for paclitaxel-induced peripheral neuropathy (PIPN)." (PMID 36059704, 2022). "sNfL: serum neurofilament light chain, EORTC QLQ-CIPN20: European Organization for Research and Treatment of Cancer Quality of Life Questionnaire-Chemotherapy-Induced Peripheral Neuropathy 20 module." (PMID 32409710, 2020). "We then investigated whether this protective effect of Carba1 was also detectable by histopathological analysis of intraepidermal nerve fiber density (IENFD) and serum concentration of neurofilament light chain (NfL), a biomarker of PTX-induced peripheral neuropathy." (PMID 41160692, 2025). "We set out to determine the usability of serum neurofilament light chain (sNfL), serum glial fibrillary acidic protein (sGFAP), and retinal parameters by using optical coherence tomography (OCT) as reliable biomarkers of the progression of oxaliplatin-induced peripheral neuropathy (OIPN)." (PMID 32409710, 2020).
psychiatric disorder (46 papers, 2012 to 2025). A disorder characterized by behavioral and/or psychological abnormalities, often accompanied by physical symptoms. "As expected, serum neurofilament light chain levels were higher in frontotemporal dementia compared to primary psychiatric diseases and controls (P < 0.001), adjusted for age, sex and geriatric depression scale." (PMID 37101834, 2023). "Another marker that has been explored in people with psychiatric disorders is cytoskeletal protein neurofilament light chain (NF-L)." (PMID 35585111, 2022). "In the majority of the cohort, neurofilament light chain concentrations were not detectable in urine (n = 6 samples above lower limit of detection (0.038 pg/ml): n = 5 frontotemporal dementia, n = 1 primary psychiatric disease)." (PMID 37101834, 2023).
cancer (40 papers, 2010 to 2026). A tumor composed of atypical neoplastic, often pleomorphic cells that invade other tissues. "Several biomarkers have recently been identified as predictors of a higher risk of developing CIPN in cancer patients undergoing chemotherapy, including neurofilament light chain." (PMID 39011110, 2024). "In our study, the majority of DEGs between LGGs are associated with normal neuronal development, like CHN1 and NEFL (NFL) are expressed in cerebral cortex and active in synaptic genesis and function, while in cancer those genes play as oncogenes." (PMID 40382536, 2025). "NEFL mRNA was down-regulated more than 1.5-fold (from 1.97 to 78.36) in 71.4% (10/14) of the lymph node samples than in their paired primary cancer tissues (P = 0.011)." (PMID 22319610, 2012). "We aimed to determine whether serum levels of neurofilament light chain (sNfL) could predict the onset and severity of CIPN, and whether sNfL levels were associated with other clinical factors in people with cancer." (PMID 41509522, 2026). "Moreover, in several studies, NEFL was regarded as a tumor suppressor gene, and its loss of heterozygosity (LOH) was related to carcinogenesis and metastasis in several types of cancer." (PMID 22319610, 2012). "DNA methylation-mediated inactivation of NEFH, NEFL and NEFM also occur in other types of cancer originated from pancreas, gastric and colon." (PMID 34001208, 2021). "In several previous studies, NEFL has been regarded as a tumor suppressor gene, and its LOH has been related to the carcinogenesis of several types of cancer." (PMID 22319610, 2012).
infection (31 papers, 2008 to 2026). The state of being infected such as from the introduction of a foreign agent such as serum, vaccine, antigenic substance or organism. "Blood-based biomarkers for CNS injury, like neurofilament light chain protein (NfL) and Glial fibrillary acidic protein (GFAp), may be valuable tools for detection and monitoring manifestation during the acute phase of this infection." (PMID 33743046, 2021).
tumor (30 papers, 2012 to 2026). "Recently, the NEFL protein is implicated in the pathophysiology of several tumors as a potential tumor suppressor." (PMID 31057612, 2019). "NEFL, a potential tumor suppresser, is associated with resistance to cisplatin-based chemotherapy, and re-expression of NEFL in HNC significantly increases the sensitivity of the cells to the drug." (PMID 25605243, 2015). "This transgenic model may have expressed EWS-FLI1 too late in cellular differentiation to cause the growth of an embryonic tumor because NEFL is only expressed in post-mitotic neurons." (PMID 27191748, 2017). "Newly described antibodies and methodological innovations such as PhIP-Seq, neurofilament light chain, and liquid biopsy are highlighted, which refine tumor search strategies and longitudinal monitoring." (PMID 41562781, 2026). "NEFL mRNA was found to be expressed in 92.3% of breast malignancies and down-regulated in lymph node metastases compared to the paired primary tumors." (PMID 22319610, 2012). "Evidence supporting a preference for axonal tissue includes the presence of neurofilament light chain protein (NF-L) within the tumor, which may explain axonal involvement and neuroaxis calcification." (PMID 39399631, 2024). "The neurofilament light (NEFL) is proposed to be a tumor suppressor gene." (PMID 36345474, 2022). "NEFL has been shown to act as a tumor suppressor in the carcinogenesis of breast." (PMID 25003827, 2014). "In addition to its influence on the nervous system, NEFL has been shown to act as a tumor suppressor." (PMID 22319610, 2012). "Significant overexpression of LPAR3 has been identified in HCC tumor margins and was interestingly overexpressed in the CCA portion of combined HCC-CCA, potentially owing to the increased aggressiveness along with NEFL and TUSC7 that were also overexpressed in the CCA portions." (PMID 40424447, 2025). "The MYOD1 and NEFL genes were not expressed in either the nontumor or tumor regions; however, a high methylation level in the reads with SNV was detected only in the tumor areas." (PMID 41187747, 2025).
central nervous system diseases (13 papers, 2020 to 2026). "As a structural scaffolding protein in the brain, neurofilament light chain (NfL) is highly specific for axonal injury and eventual neuronal cell death and shows prognostic values in various central nervous system diseases, which has not been well studied in CAA." (PMID 33221749, 2020).
brain diseases (12 papers, 2019 to 2025). "Plasma levels of cerebrospinal fluid (CSF)-derived neurofilament light chain (NfL) have been proposed as promising biomarkers reflecting neurodegeneration in AD or other related brain disorders." (PMID 36768476, 2023).
peripheral nervous system disorder (12 papers, 2021 to 2025). A disease involving the peripheral nervous system. "Neurofilament light chain (NfL) levels are sensitive biomarkers of axonal damage, increased in patients with central and peripheral nervous system disorders." (PMID 34363587, 2021). "Although CMT is described as a disease of the peripheral nervous system, CNS involvement is reported in the literature in several CMT patients by variations in the MFN2, PMP22, GJB1, GDAP, MORC-2, NDRG1 and NEFL genes." (PMID 37238449, 2023).